CD1D (CD1d molecule)
Diseases named in the same sentence as CD1D in open-access papers (continued):
Sharing a sentence is not in itself a finding about the gene and the disease.
cancer (80 papers, 2009 to 2025). A tumor composed of atypical neoplastic, often pleomorphic cells that invade other tissues. "In fact, lower expression levels of CD1d on a variety of blood cancers is associated with progressive and advanced stages of disease in both murine models and in humans." (PMID 29109728, 2017). "The mechanisms underlying CD1d downregulation or loss by cancer cells are largely unknown." (PMID 35615083, 2022). "iNKT cells, specialized T lymphocytes that recognize glycolipid antigens via CD1d, normally contribute to cancer immune surveillance and can kill CRC cells through the perforin–granzyme pathway." (PMID 41155306, 2025). "This unique cell population is a promising candidate for cell therapy for cancer treatment because of its inherent cytotoxicity against CD1d positive cancers as well as its ability to induce host CD8 T cell cross priming." (PMID 38993780, 2024). "The first mechanism is to directly recognize and eliminate cancer cells harboring CD1d via perforin/ granzyme, TNFα, TRAIL dependent apoptosis, FasL dependent apoptosis, or B cell mediated cytolysis." (PMID 38993780, 2024). "When cancer cell-derived nanovesicles were formulated to load αGC onto their surface CD1d, they efficiently activated iNKT cells." (PMID 39301248, 2024). "The CD1 family is divided into several groups, among which CD1d is widely expressed in different cancers." (PMID 37158883, 2023). "While recent evidence supports a role of cardiolipin in NKT cell responses against cancer, there remains the intriguing question of how a tetra-acylated lipid species is able to bind to CD1d." (PMID 37908366, 2023). "Both types recognize glycolipids on CD1d molecules, but their functions in cancer defense are clearly distinct." (PMID 36830717, 2023). "Firstly, iNKT cells can recognize cancer cells that express CD1d molecules via the interaction between the iNKT cell T-cell receptor (TCR) and CD1d." (PMID 37444608, 2023). "The reliance of PBMC-iNKT cells‘ cytotoxic recognition on antigen-presenting protein CD1d heavily restricts their efficacy; CD1d is limited to presenting glycolipid antigens, and multiple cancers downregulate CD1d expression to evade iNKT killing." (PMID 35886891, 2022). "Expression of CD1 molecules in cancer are associated with different clinical outcomes while associated with poor prognosis in renal cell carcinoma, CD1d promotes NKT-mediated cytolysis of cancer cells in lung adenocarcinoma." (PMID 34335558, 2021). "Although type II NKT cells are restricted to the CD1d molecule, they have a suppressive role in cancer." (PMID 32231116, 2020). "HPV has developed mechanisms to avoid NKT cytotoxicity, such as CD1d downregulation, but more studies are necessary to elucidate the role of this cell in cancer." (PMID 29976244, 2018). "CD1d-restricted invariant natural killer T (iNKT) cells are considered an attractive target for cancer immunotherapy." (PMID 30013569, 2018). "It is thus possible that ER-stressed CD1d+ cells exhibit altered self-lipid loading, such that immunogenic self-lipid antigens are presented to and activate iNKT cells in the context of cancer and other forms of sterile inflammation." (PMID 29326711, 2017). "CD1D expression was lower in nearly all carcinoma samples when compared to adjacent normal mucosa (student’s T-test, P = 1.4×10−67)." (PMID 28931069, 2017). "In conclusion, the present results propose and support monomeric CD1d-scFv antitumor fusion proteins as a potent tool to effectively harness iNKT cells against cancer." (PMID 23242316, 2013). "Despite the well-established antitumor activity of CD1d-restricted invariant natural killer T lymphocytes (iNKT), their use for cancer therapy has remained challenging." (PMID 23242316, 2013). "The ability of CD1d-restricted iNKT cells to promote antitumor immune responses has been documented in multiple human and animal cancer studies." (PMID 21695190, 2011).
cancer (continued). "CD1d ligands detected from cancer cells activate or block CD1d-restricted T cell responses." (PMID 40746558, 2025). "Additionally, CD1d-mediated lipid presentation during cancer development would allow the identification of endogenous agonists and further strategies to reduce their presentation, improving iNKT cell activation through exogenous stimulation." (PMID 39941775, 2025). "The implications of CD1d expression in cancer cells are controversial." (PMID 39941775, 2025). "Our data compliment previous findings to confirm that humanized γδ T cells expressing γδ TCR receptors may have a high affinity for human cancer cells and the CD1d-αGalCer complex, generating a robust cytotoxic effect." (PMID 40801630, 2025). "Furthermore, the outstanding antitumor effect of WTMCGEP observed in CD1d−/− mice suggests that combination therapy using this herbal mixture and other current cancer therapies prevents immunosuppression." (PMID 37152373, 2023). "Furthermore, it is imperative that such studies should be conducted in reliable preclinical humanised mouse models of cancer that display the human CD1d antigen presentation system, complemented by human iNKT cells." (PMID 37153585, 2023). "Also in human cancers CD1d is mainly expressed by the hematopoietic ones, whereas very few solid tumors are CD1d-positive." (PMID 35615083, 2022). "Upon HPV-16 E5 expression in both C33A cancer cell line and normal human keratinocytes, CD1d levels were downregulated via proteasomal degradation, with the inhibition of calnexin-related CD1d trafficking potentially protecting HPV-infected cells from immunological surveillance." (PMID 34696321, 2021). "In the context of cancer, Vδ1 γδ T cells recognize altered-self lipids presented by CD1d." (PMID 34071865, 2021). "However, iNKT cell function in advanced-stage cancer patients can be converted by α-GalCer-loaded CD1d+ cell therapy." (PMID 32231116, 2020). "Despite most of the research in iNKT cell-mediated killing activities against tumors have focused on cancer cell elimination, some studies have addressed the role of iNKT cell cytotoxicity in the control of the tumor microenvironment, especially of CD1d-positive, myeloid-derived cells." (PMID 32486268, 2020). "However, conversely, CD1d expression in human cancer has been reported to be correlated with poor prognosis in human renal cell carcinoma and multiple human hematopoietic malignancies." (PMID 29520281, 2018). "Some cancer cells are reported to express CD1d, suggesting that they may affect NKT cell-mediated antitumor immunity." (PMID 29520281, 2018). "Such ligands could be presented on CD1d, either on the cancer cells themselves, if CD1d-positive, or on antigen-presenting cells and result in different outcomes." (PMID 29375569, 2017). "Aside from regulation of CD1d expression, blood cancers may also be able to evade recognition by NKG2D on iNKT cells." (PMID 29109728, 2017). "Interestingly, in chronic lymphocytic leukemia (CLL), CD1d expression was found to increase during disease progression, counteracting the suggested role of CD1d as an anti-survival factor in cancer." (PMID 29018445, 2017). "Given the recent clinical success of adoptive T cell therapy in cancer, CD1d may be a novel target for overcoming the limitation of HLA restriction and the broadening of the application of this therapy." (PMID 27213277, 2016). "The immunoregulatory role of CD1d-restricted iNKT cells in the transactivation of innate and adaptive immune responses has been well demonstrated, and several studies have exploited iNKT cells for therapeutic cancer vaccination." (PMID 25426294, 2014). "Several clinical trials tested whether treatment with αGalCer alone, αGalCer pulsed CD1d+ APC, or other CD1d+ cell types (monocyte derived DC (moDC), mature DC, immature DC rich APCs) would activate and expand iNKT cells in vivo in patients in a variety of cancer types." (PMID 39170618, 2024).
cancer (continued). "Thus, it is tempting to speculate that CD1d-dependent regulation of CD36 functions in cancer cells could contribute to modulate their survival, proliferation and/or metastatic potential and consequently influence disease progression and response to treatment." (PMID 36344546, 2022). "First, iNKT cells are available for treating many types of cancers because all human beings share the same invariant TCR and CD1d." (PMID 36830717, 2023). "NKT cells activate the DC cells by affecting α-GalCer, strengthening the immune system response against cancer cells, and mediating the interactions between TCR and CD1d, as well as CD40L and CD40." (PMID 37158883, 2023). "However, expression of CD1d on moDC has been shown to be negatively correlated with expression of CD1a, which in turn has been suggested to be a surrogate marker for IL-12 secreting type-1 polarized moDC, the preferred functional characteristics for cancer vaccines." (PMID 26460687, 2015). "Secondly, iNKT cells can recognize CD1d-negative cancer cells using NK-like mechanisms of target cell recognition, such as NKG2D and TNF receptor ligands." (PMID 37444608, 2023). "While it has been found to be a ligand for CD1d, is also included within the lipid network promoted by mTORC2, and is slightly elevated by SK1 knockdown (data not shown), there is not much evidence for or against its role as an NKT cell antigen in cancer." (PMID 37908366, 2023). "Our previous studies have demonstrated the antitumor functions of HSC-iNKT cells in vivo when targeting CD1d positive and negative cancer cells." (PMID 36034226, 2022). "CD1d positive tumors are more susceptible to iNKT cell-mediated lysis compared to CD1d negative tumors, and cancer cells often avoid detection by downregulating CD1d, demonstrating an important role for CD1d-TCR interactions in immunosurveillance." (PMID 34680322, 2021). "While Type I NKT cells directly lyse cancer cells expressing CD1d, most solid cancers are negative for CD1d expression." (PMID 34208864, 2021). "Group 1 CD1 molecule expression is limited to CD4 and CD8 double-positive thymocytes and professional antigen presenting cells, whereas Group 2 CD1d is more broadly expressed and is present on non-hematopoietic cells, including some cancer cells." (PMID 34072042, 2021). "As it occurred in other types of cancer, iNKT cells could target cancer cells both in a CD1-dependent and CD1d-independent manner." (PMID 32486268, 2020). "Presentation of α-GalCer by CD1d-expressing APCs was indeed improved using liposomes and resulted in increased expansion and IFN-γ production by iNKT cells and a potent anti-metastatic effect in a highly malignant metastatic lung murine cancer model." (PMID 30013569, 2018). "We show that the hypermethylation does not result in lower CD1D expression than in unmethylated carcinoma." (PMID 28931069, 2017). "This would explain why no carcinoma samples are found with high CD1D expression, neither in the TCGA dataset, nor in our patient cohort." (PMID 28931069, 2017). "CD1d blockade, or the iNKT-depleting antibody NKTT120 recently developed for inflammatory diseases, could have a role in treatment of cancers in which iNKT acquire immunosuppressive functions." (PMID 25349699, 2014). "We next examined whether 6B11 mAb treatment rendered iNKT cells cytotoxic to other cancer cell lines regardless of CD1d expression." (PMID 38319156, 2024). "As HIF plays a key role in metabolism, we hypothesized that induction of HIF-1α or alterations in glycolytic metabolism may be the mechanism by which cancers regulate NKT cell responses, by either presenting activating or inhibitory lipid antigen in the context of CD1d." (PMID 39596374, 2024). "However, cytokine secretion induced in CD1d+ APCs following injection of αCD1d antibodies, has been shown to be sufficient to inhibit the growth of different CD1d-negative experimental carcinomas in mice." (PMID 38579449, 2024).
cancer (continued). "However, the lack of functional assays using these cells from cancer survivors and the use of CD1d to distinguish classical NKT cells (vs. NKT-like cells) during acute and chronic exercise currently limits our knowledge in this area." (PMID 37325799, 2023). "Non-conventional T cells recognize lipids via CD1d, and the glycolipid α-galactosylceramide (α-GalCer) is currently used in several clinical studies as an exogenous ligand to harness iNKT cells against cancer cells." (PMID 35682578, 2022). "While CD1d presence is essential for iNKT cell killing in some cancer types other studies, including this one, have demonstrated that in some contexts, antigen presentation by cancer cells might not be as important as triggering by innate mechanisms." (PMID 34535957, 2021).
hematologic malignancies (7 papers, 2020 to 2025). "Particularly, CD1d is more commonly expressed in hematological malignancies as compared to non-hematological malignancies." (PMID 38993780, 2024). "Overall, these data show that CD1d-Vδ2 bsTCE improves survival in multiple in vivo hematologic malignancy models using either expanded type 1 NKT and Vγ9Vδ2-T cells or PBMCs as effector cells and demonstrate antitumor efficacy with intermittent dosing." (PMID 36868236, 2023). "This formed the rationale for the first-in-human dose-escalation study with LAVA-051 in heavily pre-treated MM and other CD1d-positive hematologic malignancies." (PMID 34640611, 2021). "Moreover, in solid tumors and hematological malignancies, human and mouse CD1d-restricted iNKT cells reshape the TME by selectively eliminating CD1d-expressing protumor M2-like macrophages while preserving antitumor M1-like populations." (PMID 40231459, 2025). "This hypothesizes that iNKT cells may be an excellent candidate for adoptive cell therapy for hematological malignancies since all individuals have identical CD1d molecules." (PMID 38993780, 2024). "In addition, CD1d is commonly expressed in hematological malignancies." (PMID 38993780, 2024). "Further advantages of CAR iNKT cells are that they are distinct cells that can be isolated and expanded, recognize a unique marker CD1d that is frequently expressed on hematological malignancies and have cytotoxic capacity that may be augmented through other ligands." (PMID 38993780, 2024).
inflammation (4 papers, 2011 to 2019). Aberrant reaction of the microcirculation characterized by movement of fluid and leukocytes from the blood into extravascular tissues. "Intestinal NKT cells play a central role in the regulation of mucosal immunity, and dysregulation of CD1d expression and NKT cell activation have been associated with the development of intestinal inflammation in mice and humans." (PMID 29378774, 2018). "In those studies, CD1d-deficient mice and invariant NKT (iNKT)-deficient mice that lacked NKT cells were shown to be protected from the development of gut inflammation." (PMID 22539101, 2012). "IL-9 production by a subset of non-invariant (type 2) murine CD1d-restricted CD4+ NKT cells is associated with IgE production and antigen-induced pulmonary inflammation and mast cell infiltration." (PMID 22174854, 2011).
bacterial infection (3 papers, 2018 to 2022). "In contrast to the CD1d-dependent actions of iNKT cells, a cytokine-mediated, CD1d-independent iNKT cell activation was shown to limit pulmonary inflammation and a secondary bacterial infection during IAV infection." (PMID 30319649, 2018).
blood cancer (2 papers, 2017 to 2025). "Various mechanisms have been associated with downregulation of CD1d expression in blood cancers." (PMID 29109728, 2017). "The downregulation of CD1d on malignant cells is one of the major contributing factors to the evasion of iNKT cell immunosurveillance in blood cancers." (PMID 29109728, 2017).
infectious disease (2 papers, 2011 to 2024). A disorder directly resulting from the presence and activity of a microbial, viral, or parasitic agent in humans. "In these scenarios, the use of antibodies or other approaches targeting CD1d expression, trafficking or signalling could provide novel therapeutic strategies for a variety of inflammatory, autoimmune and infectious diseases." (PMID 38579449, 2024). "Thus, since lipid metabolic programs are critical in controlling immune cell function and activation, the capacity of CD1d to shape metabolic programs in macrophages opens new pathways to investigate unappreciated functions for this molecule in metabolic, inflammatory or infectious diseases." (PMID 38579449, 2024).
metabolic disease (2 papers, 2022 to 2024). A congenital disorder (due to inherited enzyme abnormality) or acquired (due to failure of a metabolically important organ) disorder resulting from an abnormal metabolic process. "Unveiling the specific CD1d-intrinsic vs. NKT-dependent functions of individual CD1d-expressing cell types in adipose tissue may help unpick the conflicting literature surrounding the CD1d-NKT axis in metabolic disease." (PMID 38579449, 2024).
immune diseases (1 paper, 2012). "To investigate whether TLR4-mediated differential production of IL-4 and IFN-γ by iNKT cells regulates iNKT cell-mediated immune diseases, we compared joint inflammation in CD1d−/− mice adoptively transferred with either WT or TLR4-deficient iNKT cells in the K/BxN serum transfer model." (PMID 23028952, 2012).
neurodegenerative disease (1 paper, 2022). A disorder of the central nervous system characterized by gradual and progressive loss of neural tissue and neurologic function. "Ningalins act as potent inhibitors against the HIV-1 virus and kinases related with neurodegenerative diseases (CDK5, GSK3b, CD1d)." (PMID 36662210, 2022). "In addition, they also show potent inhibition against kinases related with neurodegenerative diseases, such as cyclic-dependent kinase 5 (CDK5), glycogen synthase kinase 3b (GSK3b) and casein kinase I (CD1d)." (PMID 36662210, 2022).
renal disease (1 paper, 2013). "Circulating immunoglobulins (Ig), rheumatoid factor (RF), anti-DNA and anti-cardiolipin (anti-CL) antibodies, and renal disease were analyzed in these and CD1d-deficient (CD1d°) BWF1 mice that we had previously generated." (PMID 23531237, 2013).
CD1D also shares sentences with these, for which no sentence is quoted: multiple myeloma (13 papers); acute lymphoblastic leukemia (3); experimental autoimmune encephalomyelitis (3); multiple sclerosis (3); airway hyperresponsiveness (2); anaplastic carcinoma (2); chronic myeloid, (2); colon (2); colorectal cancer (2); meningitis (2); pneumonia (2); sarcoma (2); Stroke (2); abdominal aortic aneurysm (1); acute chest syndrome (1); acute graft versus host disease (1); autoimmune hepatitis (1); Borrelia burgdorferi infection (1); brain infarction (1); cardiomyopathy (1); Chagas disease (1); cholestasis (1); chorioamnionitis (1); Deficient (1); Depression (1); dermatitis (1); eosinophilic esophagitis (1); experimental arthritis (1); fungal infection (1); gingivitis (1).
A further 26 diseases each share a sentence with CD1D in 1 paper.